CASP9 (caspase 9)
Diseases named in the same sentence as CASP9 in open-access papers (continued):
Sharing a sentence is not in itself a finding about the gene and the disease.
cancer (continued). "In addition, caspase-9 and caspase-3 were observed to be cleaved in A-549 cells, indicating the activation of mitochondrial apoptosis in cancer cells." (PMID 31336900, 2019). "In addition, we observed that the pretreatment of cancer cells with quercetin improves extrinsic and intrinsic apoptosis by activating caspase-8 and caspase-9, respectively." (PMID 31528215, 2019). "By reducing mitochondrial mass and energetic metabolism, and increasing at the same time the levels of intra-mitochondrial reactive oxygen species, phenol TPP-derivatives 1 and 2 induced mitochondria depolarization and triggered a caspase 9/3-mediated apoptosis, limited to cancer cells." (PMID 29915539, 2018). "The manipulation of the alternative splicing of Bcl-x and Caspase 9 may have therapeutic potential in cancer treatment." (PMID 29788973, 2018). "Although alsterpaullone was selected as an effective adjuvant therapy for paclitaxel-treated patients, other phosphatases for caspase-9 may be more effective for their anti-cancer or drug resistance reversal effect." (PMID 29416675, 2018). "Homoharringtonine regulates the alternative splicing of Bcl-x and Caspase 9, resulting in a decreased expression of anti-apoptotic Bcl-xL and Caspase 9b with a concomitant increase in the levels of pro-apoptoticBcl-xS and Caspase 9a in various cancer cells." (PMID 29788973, 2018). "In this study, we demonstrated for the first time that HHT could regulate the alternative splicing of Bcl-x and Caspase 9 pre-mRNA in several human cancer cells." (PMID 29788973, 2018). "Additionally, EGCG is also capable of inducing cancer stem cells to apoptosis by restraining the expression of Bcl-2, followed by activating Caspase-9 and its downstream Caspase-3." (PMID 28969057, 2017). "Our results show TH has a potentiating effect on Apaf-1 and Caspase-9 at cancer tissues level." (PMID 28399853, 2017). "The alterations of phosphorylation status of AKT and its substrate GSK3β, up-regulation of pro-apoptotic regulators including caspase-3, caspase-9 and PARP, and up-regulation of cell cycle regulator p27, were implicated in the biological activity of OPCML in cancer cells." (PMID 28407749, 2017). "In addition, inhibition of miR-7641 boosted doxorubicin-mediated apoptosis of cancer cells via upregulation of apoptotic molecules Caspase 9 (CAS9) and poly ADP ribose polymerase (PARP) and downregulation of anti-apoptotic molecule BCL2." (PMID 28827731, 2017). "Furthermore, YC-1 enhanced the chemo-sensitivity of cancer cells to cisplatin by regulating expression and activity of apoptosis-related proteins, leading to the activation of caspase-9 and caspase-3 signaling." (PMID 28612710, 2017). "Previously, several studies demonstrated that quercetin inhibited inflammation, enhanced immune function and promoted apoptosis by modulating key pathways regulating cancer, such as, prostaglandin G/H synthase 2, interleukin (IL)-2, peroxisome proliferator activated receptor gamma and caspase-9." (PMID 28099904, 2017). "The cytotoxicity of Dox caused by the targeted accumulation of Dox mediated by TPP-NPs was enhanced by activating the mitochondria signaling pathway in cancer cells, demonstrating increased activity and the rapid release of cytochrome c, caspase-9, and caspase-3." (PMID 28249375, 2017). "Apoptosis-related proteins, e.g., cleaved forms of caspase-9 and caspase-3, increased after treatment with the miR-145-5p mimic, confirming that the high expression of miR-145-5p promotes apoptotic cell death in cancer cells by Pa-PDT." (PMID 28456786, 2017). "Early studies on cell death regulation dependent on the caspase-9 protein have revealed the participation of Akt and small G protein p21-Ras kinases, and the PI3K–Akt–mTOR signaling pathway dysregulation has been extensively associated with cancer." (PMID 28632179, 2017).
cancer (continued). "In this study, PA could raised the mRNA and protein expressions of caspase-3, caspase-8 and caspase-9, Res raised these effects of Res treatment, this combination done a good cancer cells apoptosis effects." (PMID 28978315, 2017). "The results showed that the two trichothecene mycotoxins induced the apoptosis of cancer cell HepG-2 via activation of caspase-9 and caspase-3, up-regulation of bax gene expression, down-regulation of bcl-2 gene expression, and disruption of the mitochondrial membrane potential of the HepG-2 cell." (PMID 27322225, 2016). "TRAIL triggers the extrinsic death receptor pathway and acetate/propionate mixture acts on cancer cells mitochondria and triggers the intrinsic cell death cascade (caspase 9 activation, ROS production, mitochondrial membrane depolarization and cytochrome c release)." (PMID 26771233, 2016). "Initiator caspase-9 is involved in the mitochondrial pathway of apoptosis induction and its activity has been found in several cancer cell lines and also in non-cancer cells after taxane application." (PMID 25685064, 2015). "The cancer-restricted role of hnRNP L in caspase-9 AS is apparently due to NSCLC-specific phosphorylation of hnRNP L on Ser52, suggesting that cancer cell developed a device to switch an ubiquitous RBP into a prooncogenic protein through a specific posttranslational modification." (PMID 26273627, 2015). "Preliminary in vitro experiments confirm that UDCA can induce cancer cell apoptosis by promoting caspase-3, caspase-8, caspase-9, Bax, Fas/FasL, TRAIL, DR4, DR5 and IκB-α gene expression in cancer cells, and reduce the expression of Bcl-2, Bcl-xL, XIAP, cIAP-1, cIAP-2, survivin and NF-κB." (PMID 25951128, 2015). "Since the majority of anticancer strategies initiate apoptosis through caspase 9 activation, the modulation of caspase 9 expression may be exploited by designing new ways to control apoptosis in malignant tumors, including GBM." (PMID 25852394, 2015). "Upon treatment with proteinase K-activated parasporin-2Aa1, morphological changes were observed and western blot analysis revealed the cleavage of poly (ADP-Ribose) polymerase, caspase-3 and caspase-9 in cancer cell lines exclusively, indicative of programmed cell death, apoptosis." (PMID 26263002, 2015). "Therefore, caspase-9 mediates Puma activation to determine the threshold for overcoming chemoresistance in cancer cells." (PMID 25356864, 2014). "Additionally, Bcl-2 family proteins participate in maintenance of MMP regulation of the release of mitochondrial Cyt c to the cytosol and activation of caspase-9 activity which contribute to apoptosis of cancer cells." (PMID 24959718, 2014). "The main mechanism by which manuka appears to exert its anti-proliferative effect on cancer cells is through the activation of the intrinsic apoptotic pathway, involving the induction of the initiator caspase-9 which in turns activates the executioner caspase-3." (PMID 23409104, 2013).
cancer (continued). "X-linked inhibitor of apoptosis protein (XIAP) is constitutively expressed endogenous inhibitor of apoptosis, exhibit its antiapoptotic effect by inactivating key caspases such as caspase-3, caspase-7 and caspase-9 and also play pivotal role in rendering cancer chemoresistance." (PMID 23613836, 2013). "We assumed that the intrinsic apoptosis pathway induced by MBS extract in the treated cancer cells might be provoked via direct upregulation of caspase 9 gene, via the activation of caspase 8 by the extrinsic pathway, or via the upregulation of Bax gene." (PMID 23122182, 2012). "Therefore, it is possible that “higher production” for CASP9 in G or C carriers offer protection against the development of some cancers." (PMID 22616010, 2012). "We have shown that enhancement 0.6 or 1.2 nmol/kg (0.3–0.6 mg/kg)of Dox-induced apoptosis by Sch B in cancer cells was associated with the activation of caspase-9 rather than caspase-8." (PMID 22164272, 2011). "In discordance with this prediction, the gene encoding the initiator caspase of the intrinsic pathway, caspase-9 is neither mutated nor silenced in the majority of cancers." (PMID 24281211, 2010). "Furthermore, our results indicate that LY294002 causes inhibition of tumor growth and increase in lumen formation in C4-HI cancer cells through an intrinsic BAX/mitochondrial/activated caspase-9 apoptotic mechanism." (PMID 20520761, 2010). "On the other hand, signaling pathways, such as PI3K/Akt or the Ras/MAPK pathway, often are hyperactivated in cancer cells and may prevent apoptosis by various means, i.e., by phosphorylation of Bcl-2 family proteins or of caspase-9." (PMID 24281211, 2010). "To assess whether the same mechanisms are operating in human cancer, we tested the expression levels of the caspase-3 and caspase-9, p21waf1, and p-JNK in MCC and CRC cells lines." (PMID 19243219, 2009). "Importantly, 17-Octadecynoic acid may act as an enzyme inhibitor and has anti-cancer potential, which could contribute to the regulation of apoptotic markers (Casp3, Casp9) and suppression of DBP-induced cell death." (PMID 40792058, 2025). "Therefore, MP28 induces cancer cell apoptosis through the caspase-9 signaling pathway." (PMID 41440915, 2025). "Based on these reports, the anti-cancer properties of berberine can be regarded by stimulating both endogenous and exogenous apoptosis via increasing the protein expression of pro-apoptotic molecules Bax, Bad, Bak, and activating Caspase-3, Caspase-8 and Caspase-9." (PMID 40490812, 2025). "Intriguingly, the gene expression levels of BCL2, CDK2, MDM2, Casp9 and P21 were reversed in HeLa cells treated with L. cornuta ethyl acetate fraction when compared with the untreated HeLa cells, indicating its potential to regulate cell proliferation, apoptosis, and cell cycle in cancer cells." (PMID 39005932, 2024). "Therefore, the increase in caspase-8 and caspase-9 mRNA expression in MDA-MB-231 cells could potentially contribute to the inhibition of cancer cell growth and the induction of cell death." (PMID 38227157, 2024). "The study reported a comprehensive anticancer mechanism of eugenol against cancer cell lines, involving the promotion of translocation of the pro-apoptotic gene Bax, a decrease in the anti-apoptotic gene Bcl-2, the release of cytochrome c, and the activation of caspase-9 and caspase-3." (PMID 39416730, 2024). "Caspase-9 should be activated via plenty of intrinsic proteins and small molecules to maintain its catalytic status; otherwise, pathophysiological outcomes may occur, leading to degenerative disorders or cancer." (PMID 39866644, 2024).
cancer (continued). "The cell response to Caspase 8 and Caspase 9 expression pattern at higher doses of MuSCF-NPs, can be attributed to the cancer cell compensatory mechanisms and anti-apoptotic gene-regulators recovering process, which lead to the drug-resistant potential of cancer cells." (PMID 38600497, 2024). "Consequently, the Th-nanoemulsion has a potential anticancer effect as it reduces the growth and proliferation of HepG2 and MCF-7 cancer cells, increases apoptosis by increasing casp-8 and casp-9 activities, and finally lowers the level of VEGFR-2 concentrations." (PMID 37836753, 2023). "Further in vitro experiments showed that TAX could significantly induce cancer cell apoptosis as verified by increased pro-apoptotic molecules including Bax, caspase-9, and PARP1 downregulated anti-apoptotic protein Bcl-2; and decreased mitochondrial potential." (PMID 36230568, 2022). "CASP9 may be involved in multiple cancers, autoimmune disorders, and neurological diseases." (PMID 36552744, 2022). "The up-regulation of Casp3 and Casp9 gene expression suggested that the treatment of Panc1 and Pc3 cells with the tested extracts induces mitochondrial dysfunction by discharging cytochrome c and inducing the intrinsic pathway apoptosis of cancer cells caspases 3 and 9 activations." (PMID 36386915, 2022). "Carrageenan mechanism in inhibiting the growth of cancer cells has also been investigated, where carrageenan is able to induce the process of apoptosis through activating the pathways of caspase-3, caspase-8, and caspase-9; remodulation of the Bax:Bcl-2 ratio; and DNA damage." (PMID 34064093, 2021). "The accumulation of caspase-9 may induce degenerative and developmental diseases, including cancer." (PMID 34288800, 2021). "Based on the importance of CASP9 for cell apoptosis and the current acknowledged anti-apoptotic function of NF-κB in cancer, we think it is necessary to study whether NF-κB regulates the CASP9 gene, which may provide new insight into the potential pro-apoptotic role of this TF." (PMID 32225068, 2020). "Thus, phosphorylation of caspase-9 at Thr125 may be the target of various oncogenic kinases and a valuable marker for the prediction of cancer patient prognosis." (PMID 29416675, 2018). "Therefore, this review is to summarize recent pertinent literature on the comprehensive description of the molecular events implicated in caspase-9 activation and inhibition, as well as the clinical trials in progress to give deep insight into caspase-9 for suppressing cancer." (PMID 28177918, 2017). "In spite of the fact that both caspase-3 and caspase-9 have been implicated in non-apoptotic functions, the activation of these enzymes in cancer cell cultures can still be regarded as an indication of apoptotic execution and initiation of its intrinsic pathway, respectively." (PMID 25692552, 2015). "We have generated a new cell penetrating peptide that specifically binds to PP2Ac (DPT-C9h or DPT-C9), targets caspase-9/PP2Ac interaction, leading to caspase-9 activation, mitochondrial membrane permeabilization, cytochrome c release and apoptosis in a variety of human and mouse cancer cell lines." (PMID 23637769, 2013). "The direct promotion of cancer cell survival and the inflammation-induced chemoresistance have been linked to the hyperactivation of NF-κB in cancer cells, which induces upregulation of antiapoptotic proteins such as c-FLIP and XIAP, and inhibition of proapoptotic proteins such as Bax and Caspase-9." (PMID 20871832, 2010). "Overexpression of EMP1 leads to increased apoptosis via caspase-9, reduced VEGF-C expression, and diminished cancer cell ‘stemness’." (PMID 41465326, 2025).
cancer (continued). "For example, it was found that the ROS/caspase-9/caspase-3 apoptotic pathway was activated by CAP exposure, leading to Gasdermin E (GSDME) lysis and cancer cell pyroptosis." (PMID 40649322, 2025). "For example, luteolin prevents cancer via modulation of numerous pathways—inactivates proteins, such as procaspase-9, CDC2, and cyclin B or upregulates caspase-9 and caspase-3, cytochrome C, cyclin A, CDK2, and APAF-1." (PMID 41304998, 2025). "Survivin, (IAP) family, is commonly overexpressed in cancer cells and inhibits apoptosis by directly targeting key effectors such as CASP3 and CASP9." (PMID 40405479, 2025). "Investigating the molecular mechanism of apoptosis in human cancer cell lines (Mcf-7, Caco-2, and A-549) induced by the 60-min tryptic BLG hydrolysate necessitated estimating caspase-9 expression." (PMID 39866644, 2024). "As shown, in pCan-1 primary cancer cells, IMT1 (1 μM) treatment significantly increased the Caspase-3 activity and the Caspase-9 activity." (PMID 39227564, 2024). "Expectedly, the PA-MSHA and Gefitinib combination resulted in increased caspase-3/caspase-9 cleavage and inhibition of EGFR-dependent activation of the AKT/ERK pathway involved in cancer cell survival." (PMID 38339275, 2024). "The assumption of the present assay was to evaluate caspase-9 activity in MCF-7 and MDA-MB-231 cancer cells after 24 h of incubation with the tested compounds." (PMID 39199694, 2024). "The results of qRT-PCR showed that the treatment of cancer cells with L. buchneri MVs led to a remarkable enhancement in the expression of BAX, CASP3, and CASP9 genes." (PMID 38326490, 2024). "Transcriptional upregulation of caspase 3, caspase 9, bax, and SOD1 genes confirms mitochondria- dependent apoptosis in the cancer cell lines." (PMID 37298090, 2023). "HECTD3, a member of the third subfamilies of HECT ligases, was validated to target and ubiquitinate caspase-9, c-MYC, and TRAF3 in cancers, already." (PMID 37031183, 2023). "Our result identified the FADD, TNFRSF1A, CASP9, MLKL, and CASP4 involved in the PANoptosis process and significantly affect patient survival, which can provide future direction in cancer research." (PMID 36874021, 2023). "The results demonstrate that oncolytic NDV delivered by MSCs effectively reduced cancer cell proliferation, induced CD8+ T cell cytolysis response, and upregulated caspase-9 expression." (PMID 37629483, 2023). "Based on the cancer panel, we uncovered that there was up‐regulation in several markers, including GADD45 and CASP9, whilst there was down‐regulation in markers like APAF‐1 and MCM2." (PMID 38938916, 2023). "Numerous cancer types have elevated levels of PARP, pro-caspase-3, and pro-caspase-9, and these aberrant expressions indicate that these markers play important roles in the development of oncogenic transformation." (PMID 37627094, 2023).